MIR1247 (microRNA 1247)
Synonyms: hsa-mir-1247; MIRN1247; mir-1247
Gene: MicroRNA gene on chromosome 14 (101,560,287 to 101,560,422, reverse strand). Ensembl gene ENSG00000283857.
Homologues: Orthologues: chimpanzee ptr-mir-1247 (100% identical).
Diseases named in the same sentence as MIR1247 in open-access papers:
MIR1247 is named in the same sentence as 6 diseases in open-access papers, as found by Europe PMC text mining. Sharing a sentence is not in itself a finding about the gene and the disease. The quoted sentences say what the papers report.
colon adenocarcinoma (1 paper, 2018). "PCNXL3 was reported to be one of the top 20 genes with the highest correlations with colon adenocarcinoma, MIR4285 and MIR3648 were shown to be differentially expressed in colon adenomas, and MiR1247 as a potential tumor suppressive gene." (PMID 29876008, 2018).
diabetes (1 paper, 2016). "Others including Mir1247 (-86.22) and Mir142b (-42.04) where expression changes in diabetes were not significantly returned to normal levels by treatment." (PMID 27855634, 2016).
gastric cancer (1 paper, 2020). A primary or metastatic malignant neoplasm involving the stomach. "The regulation of MIR941 and MIR1247 was associated with gastric cancer cell growth and migration." (PMID 32783399, 2020).
tumor (2 papers, 2018 to 2020). "MIR133b, MIR1247, and MIR1228 expression was not increased in the tumor tissue in comparison to matched adjacent nontumor tissue (cohort 1, n = 29)." (PMID 31879968, 2020).
MIR1247 also shares sentences with these, for which no sentence is quoted: cancer (1 paper); colon adenoma (1).